INS (insulin)
Diseases named in the same sentence as INS in open-access papers (continued):
Sharing a sentence is not in itself a finding about the gene and the disease.
Hyperglycemia (continued). "In patients with hyperglycemia treated with insulin, glucagon excess contributes—at least in part—to poor glycemic control and may therefore be targeted through inhibition of glucagon secretion or action." (PMID 41149695, 2025). "Furthermore, exocrine pancreatic insufficiency disrupts incretin signaling, reducing insulin secretion and worsening hyperglycemia." (PMID 41323971, 2025). "Of note, the initial weight gain with initiating insulin may be secondary to water retention from increased hydration of lean tissues as hyperglycemia resolves." (PMID 40870444, 2025). "Additionally, the autophagic degradation of two hepatic glucose transporters, namely GLUT2 (insulin-independent) and GLUT4 (insulin-dependent), during hyperglycemia was motivated via PERK/eIF2α/ATF4/CHOP, thereupon decreasing glucose uptake." (PMID 40298635, 2025). "Moreover, the insulin resistance in tissues, and an inadequate compensatory insulin-secreting response, generates hyperglycemia in patients." (PMID 41304994, 2025). "However, hyperglycaemia remains common, with many patients spending 6–7 h per day above 180 mg/dL, underscoring the need for systems that can achieve full automation of insulin delivery." (PMID 41157817, 2025). "Analysis of the Kyoto Encyclopedia of Genes and Genomes (KEGG) pathway highlighted significant enrichments of several metabolic pathways, among which insulin secretion and T2D mellitus were listed at the top, aligning with the hyperglycemia and β-cell dysfunction observed in AE males." (PMID 39934105, 2025). "Consequently, this contributes to increased glucose production and reduced insulin sensitivity, exacerbating hyperglycemia in T2DM." (PMID 40650008, 2025). "Hyperglycemia is also a common side effect, resulting not only from impaired insulin secretion from normal pancreatic cells and increased insulin resistance, but also through the specific suppression of pathologic insulin secretion from tumor cells in insulinoma patients." (PMID 41561059, 2025). "In addition, patients with severe or postoperative surgery often suffer from hyperglycemia due to stress, so strict monitoring of blood glucose and intensive insulin therapy strategies would be implemented." (PMID 40692592, 2025). "Furthermore, PNLP-3 alleviated hyperglycemia in insulin-resistant HepG2 cells by enhancing glucose consumption and glycogen synthesis." (PMID 40005141, 2025). "Additionally, AAPs block 5-HT2C in pancreatic β-cells, resulting in a decrease in insulin secretion and hyperglycaemia." (PMID 41302979, 2025). "For example, the administration of ILE can increase free fatty acid levels, leading to reduced insulin sensitivity in peripheral tissues, impaired glycolysis, and increased gluconeogenesis—all of which may contribute to hyperglycemia in preterm infants." (PMID 40567525, 2025). "Additionally, there was an increased rate of hyperglycemia with ketosis in some patients, particularly those who reduced their insulin doses too aggressively." (PMID 40707821, 2025). "Insulin exerts its glucose-lowering effect primarily by facilitating cellular uptake of glucose and suppressing hepatic glucose production, thereby directly addressing hyperglycemia common in PTDM." (PMID 40995094, 2025). "Biochemically, overfeeding manifests as hyperglycemia resistant to insulin therapy (blood glucose persistently >180–200 mg/dL despite escalating insulin requirements), hypertriglyceridemia (>300–400 mg/dL), and elevated liver function tests (ALT/AST elevation >2–3 times baseline)." (PMID 41295247, 2025). "Importantly, the improvement in HbA1c with SGLT2i did not occur at the expense of increased hypoglycaemia, representing a clear advantage over increased insulin doses for treating hyperglycaemia." (PMID 40130476, 2025).
Hyperglycemia (continued). "At the molecular level, T2DM is manifested by the activation of serine kinase cascades due to hyperglycemia and ROS that dysregulate the insulin signaling mechanism in the phosphatidylinositol 3-kinase/AKT (P13K/AKT) pathway, which is implicated in insulin secretion and glucose transfer." (PMID 40143138, 2025). "Type II cows often exhibit elevated BHB and NEFA without severe hypoglycemia, and may present hyperinsulinemia, impaired insulin signaling, and even hyperglycemia, reflecting systemic insulin resistance." (PMID 41463929, 2025). "A previous study found that systemic hyperinsulinemia due to hyperglycemia caused by PI3K inhibitors would make these agents ineffective, and that administration of ketogenic diets to suppress insulin feedback enhances the efficacy of PI3K inhibitors in mouse model." (PMID 40638603, 2025). "Sleep disturbances and insomnia can increase inflammatory cytokines (hs-CRP, tumor necrosis factor, interleukin 6) and enhance the hypothalamic-pituitary-adrenal activity, leading to reduced β-cell function, increased insulin resistance, and contributing to hyperglycemia." (PMID 41114778, 2025). "In addition, Hyperglycemia drives mitochondrial overproduction of ROS, disrupting insulin signaling pathways, worsening metabolic dysfunction." (PMID 41235339, 2025). "The primary treatment for T1D involves regular insulin injections to control hyperglycemia." (PMID 40416990, 2025). "In rare cases, hyperglycemia may persist postpartum, in which case insulin or glyburide may be prescribed, as both are considered safe for use during breastfeeding without adverse effects on the infant." (PMID 40076938, 2025). "This raised questions about whether hyperglycemia stemmed from β-cell dysfunction, insulin resistance, or both." (PMID 40509433, 2025). "However, treatment differs with insulin typically being advocated as a first-line treatment for hyperglycaemia posttransplantation to rest the pancreas and avoid the development of PTDM." (PMID 41013432, 2025). "Under conditions of hyperglycemia/hyperinsulinemia, PKCζ is activated and drives pancreatic β‐cell proliferation via the mammalian target of rapamycin (mTOR)–cyclin D2 axis, thus helping to preserve insulin secretory capacity." (PMID 41244006, 2025). "Moreover, increased SCFA levels are positively correlated with improved insulin sensitivity, which helps reduce the hyperglycemia-induced filtration burden on the kidneys." (PMID 41048444, 2025). "We can answer this question by suggesting that perhaps TSC22D1 simply acts within a feedback loop to fine‐tune insulin secretion, or it might also act as an inhibitor of insulin secretion upon prolonged hyperglycemia to prevent beta cell exhaustion." (PMID 40679946, 2025). "The hydrogel reversed hyperglycemia within 1 h following insulin administration (1.25 g/kg)." (PMID 40292663, 2025). "The older age at diagnosis in SIDD compared with type 1 diabetes, along with a relatively later start of insulin therapy and persistent hyperglycaemia, may explain the higher frequency of retinal microangiopathy observed in SIDD." (PMID 40164944, 2025). "GDM arises as the mother’s insulin secretion cannot compensate for the existing hyperglycaemia." (PMID 39861104, 2025). "Significantly, the ZMYM2 heterozygous mutant mouse model also exhibits metabolic abnormalities, including chronic mild hyperglycemia (progressively elevated blood glucose levels until 90 days of age), significantly reduced fasting serum insulin, and impaired insulin secretion capacity." (PMID 41306918, 2025). "Factors like reduced physical activity and hyperglycemia exacerbate insulin sensitivity issues." (PMID 41323015, 2025). "Multiple relevant studies conclude that women with concomitant fasting and post-load hyperglycaemia share the most severe metabolic phenotype, in terms of insulin sensitivity, insulin secretion, and adverse perinatal outcomes, followed by women with isolated fasting hyperglycaemia." (PMID 40779219, 2025).
Hyperglycemia (continued). "However, when blood glucose exceeded 200 mg/dL, the insulin infusion rate was increased by 0.5 units per hour to correct hyperglycemia." (PMID 39931500, 2025). "Hyperglycemia was the most frequent treatment-related adverse event (51.5%), alongside nausea, decreased appetite, diarrhea, and vomiting; importantly, hyperglycemia was manageable through dose adjustment, treatment interruption, and concomitant antidiabetic medication (e.g., metformin or insulin)." (PMID 41256331, 2025). "Characteristic parameters of T2DM include the following: rare ketoacidosis and hypoglycemia, usually mild hyperglycemia, decreased peripheral insulin sensitivity, normal or decreased hepatic insulin sensitivity, high levels of insulin and PP, normal or high glucagon levels, normal or low GLP-1." (PMID 39859258, 2025). "Glucose-to-insulin ratios were also less (p < 0.05) during hyperglycemia than at basal conditions." (PMID 40559370, 2025). "Therefore, hyperglycemia translates to a high glucose flux to hepatocytes in an insulin-independent manner." (PMID 40757798, 2025). "Maternal hyperglycemia-induced oxidative stress leads to higher release of oxidative stress markers in the circulation of women with GDM, which in turn can cause beta cell dysfunction and apoptosis, impaired insulin secretion, and insulin resistance." (PMID 40559375, 2025). "Furthermore, catecholamine use was associated with immunosuppression, bacterial growth, increased bacterial virulence, biofilm formation, insulin resistance, and hyperglycemia." (PMID 41302120, 2025). "Although human trials remain limited, animal studies suggest promising outcomes, indicating that Lactobacillus plantarum may help mitigate hyperglycemia and improve insulin sensitivity." (PMID 39997751, 2025). "Protective nutrition can not only reduce the incidence of hyperglycemia, but also reduce the use of insulin, which may be more suitable for severe patients." (PMID 40416376, 2025). "In infants, hyperglycemia may occur in the context of infection through the stress response, reduced insulin secretion, and diminished peripheral glucose utilization." (PMID 41552160, 2025). "This shows that FMN has the effect of regulating insulin sensitivity and alleviating hyperglycemia." (PMID 40708775, 2025). "Continuous monitoring is essential to avoid rebound hyperglycemia, which could lead to endogenous insulin release and recurrent hypoglycemia." (PMID 41235387, 2025). "Upon entering the second trimester, hyperglycemia stimulates the fetus to secrete insulin." (PMID 40510888, 2025). "Additionally, women with combined hyperglycemia exhibited mixed metabolic dysregulation and a higher incidence of insulin use, similar to previous reports that noted increased insulin resistance and higher risks of perinatal complications in this subgroup." (PMID 40569563, 2025). "This could pave the way for developing targeted therapies that enhance insulin action, reduce hyperglycemia, and slow the progression of T2DM and related complications." (PMID 40282289, 2025). "Patients requiring insulin to control hyperglycaemia had a sensor (Dexcom G4 or G6) attached." (PMID 41146739, 2025). "However, in insulin-resistant states, cells in the liver, muscles, and adipose tissue fail to respond efficiently to insulin, leading to hyperglycemia, dyslipidemia, and metabolic stress." (PMID 41235339, 2025). "Notably, the experimental suppression of FMO3 in insulin-resistant mice effectively inhibited FoxO1, a key metabolic regulatory node, and completely circumvented the progression of hyperglycemia, hyperlipidemia, and atherosclerosis." (PMID 40395816, 2025). "Furthermore, two participants required adjunctive insulin glargine with the bionic pancreas due to prolonged hyperglycaemia despite exceeding maximum insulin allowances by the algorithm." (PMID 40718205, 2025).
Hyperglycemia (continued). "Myelinating Schwann cells are primarily responsible for forming the myelin sheath around axons, but in DPN, they often exhibit metabolic dysregulation due to the effects of hyperglycemia and disrupted insulin signaling, leading to myelin sheath abnormalities and nerve function impairment." (PMID 40828619, 2025). "Indeed, treatment of patients with PI3K inhibitors leads to hyperglycaemia presumably due to the blocking of insulin-stimulated glucose uptake." (PMID 40354343, 2025). "The low insulin levels suggest that the reduced response could be the result of decreased pancreas responsivity, potentially due to the effect of maternal hyperglycaemia on the developing pancreas." (PMID 40021748, 2025). "Postprandial hyperglycemia, especially in the early morning hours, is common in gestational diabetes, and the use of glucocorticoids for fetal lung maturation can increase post-prandial glucose levels, leading to rapid changes in insulin requirements." (PMID 40340929, 2025). "Clinically, intranasal insulin reduces postprandial hyperglycemia." (PMID 41463606, 2025). "From a biological standpoint, sex-related differences in hepatic glucose metabolism and insulin sensitivity during puberty may transiently accentuate hyperglycemia in boys, thereby increasing the likelihood of clinical recognition." (PMID 41367630, 2025). "Consequently, it damages the insulin-producing islet β-cells, resulting in hyperglycemia and a significant decrease in insulin secretion within 48 h post-injection." (PMID 39820827, 2025). "Following insulin treatment to correct hyperglycemia, only LHR showed a significant decrease." (PMID 40564795, 2025). "Also, the results of a glucocorticoid‐induced glucose metabolism impairment model showed that GLP‐1RA administration prevented beta‐cell dysfunction and consequently hyperglycemia by stimulating insulin secretion and delaying gastric emptying." (PMID 40914967, 2025). "In addition to insulin’s role in regulating perfusion, hyperglycemia can also lead to the production of advanced glycation end products (AGEs)." (PMID 40469431, 2025). "While HbA1c 9.49% argues for chronically inadequate glycaemic control, we acknowledge that acute physiological stress can precipitate transient insulin resistance, and therefore the observed hyperglycaemia likely reflects a combination of poor long-term control and stress hyperglycaemia." (PMID 41275090, 2025). "Additionally, NF-κB activation in endothelial cells contributes to vascular complications, and in pancreatic β-cells, it impairs insulin secretion and promotes apoptosis, exacerbating hyperglycemia." (PMID 40136728, 2025). "The pathophysiology underlying this dysfunction may be attributed to oxidative stress induced by acute glucose fluctuations, chronic hyperglycemia, and diminished NO production, resulting from selective insulin resistance in ECs." (PMID 40093018, 2025). "It is not only necessary to ensure that insulin is delivered accurately according to the prescribed dose, but also to avoid over-infusion or under-infusion, to prevent the occurrence of hypoglycemia or hyperglycemia events." (PMID 40465596, 2025). "Additionally, AFs induce oxidative stress, which damages pancreatic β-cells responsible for insulin production, thereby impairing insulin secretion and contributing to hyperglycemia." (PMID 40864090, 2025). "As carbohydrates are the major contributor to post prandial hyperglycemia and subsequent insulin secretion, it seems logical that to achieve sodium balance and insulin homeostasis it is necessary to modify the diet, by substitution of carbohydrates with lower carb alternatives." (PMID 40248508, 2025). "The problem of poor insulin secretion and post-meal hyperglycaemia would remain, I explained." (PMID 40316731, 2025). "Numerous studies indicate that inhibiting inflammatory factor release could ameliorate insulin signaling and reduce hyperglycemia." (PMID 40941112, 2025).
Hyperglycemia (continued). "However, progressive β-cell dysfunction—driven by glucotoxicity, lipotoxicity, oxidative stress, and chronic inflammation—eventually leads to inadequate insulin secretion and overt hyperglycemia." (PMID 41012437, 2025). "Chronic hyperglycemia due to suboptimal insulin use can lead to muscle breakdown." (PMID 40163174, 2025). "Blood glucose levels should therefore also be monitored, and insulin therapy might be required in managing blood glucose levels to avoid the adverse effects of hyperglycemia." (PMID 40430135, 2025). "For T3cDM, characteristic parameters include the following: rare ketoacidosis, mild hyperglycemia, common hypoglycemia, increased peripheral insulin sensitivity, decreased hepatic insulin sensitivity, insulin, glucagon, PP and GIP levels are low, and any typical age of onset." (PMID 39859258, 2025). "Consequently, persistent hyperglycemia and ER stress contribute to β-cell dysfunction and eventual apoptosis, undermining insulin production and promoting hyperglycemia in a vicious cycle." (PMID 40534855, 2025). "Hyperglycemia induced by these processes may even lead to glucotoxicity in beta cells, which further reduces insulin secretory function." (PMID 40469441, 2025). "Moreover, hyperglycemia promotes elevated peripheral utilization of insulin, which reduces insulin transport into the brain." (PMID 40379890, 2025). "Hence, the maternal pancreas continues to increase insulin production and secretion, to prevent hyperglycemia." (PMID 40235646, 2025). "Insulin is the accepted pharmacological treatment for hyperglycaemia in pregnancy." (PMID 41246123, 2025). "Additionally, it inhibits the expression of Cluster determinant 36 (CD36), a hyperglycemia-induced fatty acid transporter, that increases free fatty acid uptake and reduces insulin secretion." (PMID 41234236, 2025). "The increased tau phosphorylation in T1D mice may result from the combined effects of hyperglycemia, oxidative stress, and impaired insulin signaling." (PMID 40862739, 2025). "As such, this study highlighted that some FCLS algorithms may prioritise avoidance of hypoglycaemia, especially overnight, by potentially under-delivering insulin during periods of hyperglycaemia." (PMID 40718205, 2025). "The schematic in 1b shows how nutrition sources change over the first 10 days of life, together with the most common metabolic complications, using the daily frequency of insulin-treated hyperglycaemia and additional phosphate supplementation based on previous data in this population." (PMID 41149637, 2025). "Insulin therapy plays a crucial role in managing hyperglycemia in AP." (PMID 40937420, 2025). "muricata may enhance glucose tolerance and insulin sensitivity, potentially benefiting the management of both fasting and postprandial hyperglycemia." (PMID 40091984, 2025). "By stimulating insulin release and enhancing insulin action, OCN could counteract the acute stress-induced hyperglycemia and insulin resistance driven by high cortisol and catecholamines." (PMID 40727110, 2025). "Modulating their expression through targeted miRNA-based therapies could restore insulin sensitivity and mitigate hyperglycemia." (PMID 40282289, 2025). "Hyperglycemia (chronic high HbA1c) → microvascular injury; insulin dysregulation → neuronal damage." (PMID 40842786, 2025). "Therefore, when hospitalized patients present with more than two blood glucose levels above 180 mg/dL in 24 h, any hyperglycemia above 250 mg/dL, or are already using insulin at home, an effective hyperglycemia treatment should be implemented." (PMID 39939862, 2025). "If hypoglycemia or hyperglycemia persists, PN dextrose or insulin rates must be recalibrated." (PMID 41295247, 2025). "Together with the earlier OGTT results, these data suggest that the reason Cyp17a1 KO female’s blood sugar levels were higher was not due to an issue with insulin secretion, but rather due to hyperglycemia, which caused the blood sugar to be elevated overall." (PMID 41385510, 2025).